POSTN (periostin)
Diseases named in the same sentence as POSTN in open-access papers (continued):
Sharing a sentence is not in itself a finding about the gene and the disease.
Hepatic steatosis (7 papers, 2016 to 2025). Steatosis is a term used to denote lipid accumulation within hepatocytes. "High levels of serum periostin have been associated with poor prognosis of different liver diseases, including hepatic steatosis, inflammation and fibrosis." (PMID 32760059, 2020). "Our previous study, as well as other findings, showed that periostin, encoded by Postn, could promote hepatic steatosis, inflammation, and fibrosis." (PMID 39872077, 2022). "In the case of metabolic disease, there is experimental evidence implicating POSTN in hepatic steatosis, inflammation, and fibrosis." (PMID 41190635, 2025). "Antisense oligonucleotides (ASOs) targeting periostin lowered hepatic steatosis in conjunction with reduced expression of α-SMA, collagen I, and other fibrotic markers and increased expression levels of PPAR-α." (PMID 36611844, 2022). "In a mice model of dexamethasone (DEX)-treated fatty liver, DEX induced a higher degree of periostin expression in white adipose tissues, driving liver steatosis in a systemic organ-mediated fashion." (PMID 36611844, 2022). "Administration of a Periostin-neutralizing antibody or genetic ablation of Periostin largely attenuated DEX-induced hepatic steatosis in mice." (PMID 31918919, 2020). "We further found that DEX upregulated the expression levels of Periostin in white adipose tissues, which in turn promoted liver steatosis." (PMID 31918919, 2020). "•DEX treatment upregulates Periostin in white adipose tissues, which in turn induces liver steatosis in mice." (PMID 31918919, 2020). "•Genetic ablation or pharmacological inhibition of Periostin partially attenuated DEX -induced hepatic steatosis in mice." (PMID 31918919, 2020). "Our findings provided a novel insight that GCs could promote liver steatosis through integrative organ crosstalk mediated by white fat-secreted Periostin." (PMID 31918919, 2020). "We further show that DEX could upregulate the expression levels of Periostin in white adipose tissues, which in turn contributes to liver steatosis and hyperglycemia." (PMID 31918919, 2020). "We further found that DEX could upregulate the expression levels of Periostin in white adipose tissue, which in turn induced liver steatosis." (PMID 31918919, 2020). "Recent studies have shown that Periostin could promote liver steatosis and through suppression of PPARα and fatty acid β-oxidation." (PMID 31918919, 2020).
IgA nephropathy (7 papers, 2020 to 2024). "In the renal tissues of patients with focal segmental glomerulosclerosis, IgA nephropathy, and lupus nephritis, periostin expression were significantly upregulated." (PMID 39570100, 2024). "De novo overexpression of periostin was found in several renal diseases such as lupus nephritis, diabetic nephropathy, IgA nephropathy, and focal-segmental glomerulosclerosis." (PMID 35268356, 2022). "Recent studies have reported the importance of periostin as a tissue or urinary biomarker in type 2 diabetes, lupus nephritis, and IgA nephropathy." (PMID 34607314, 2021). "In patients with IgA nephropathy, urine periostin levels were highly correlated with renal histological findings and were closely related to long-term kidney prognosis." (PMID 34607314, 2021). "Moreover, periostin (POSTN) has been identified as one of key genes and is significantly upregulated in IgA nephropathy (IgAN) with enhancing mesangial cell proliferation." (PMID 35967373, 2022).
Nephropathy (7 papers, 2012 to 2022). A nonspecific term referring to disease or damage of the kidneys. "Periostin overexpression was observed in patients with different types of progressive nephropathies, including lupus nephropathy and chronic allograft nephropathy (CAN)." (PMID 34768419, 2021). "Periostin staining was predominant in the injured regions, both in experimental hypertensive and human nephropathy." (PMID 22403621, 2012). "Therefore, urinary periostin might prove to be a sensitive biomarker to detect renal tubular injury of incipient nephropathy." (PMID 25884625, 2015). "Increased urinary periostin levels were described in CKD, polycystic kidney disease (PKD), and various types of nephropathies, including IgA nephropathy (IgAN)." (PMID 34768419, 2021).
allergic conjunctivitis (6 papers, 2021 to 2024). "This would be in line with a role for periostin (and IL-13) in mucosal immunity as suggested by the presence of excess periostin and IL-13, in tear fluid from patients with severe allergic conjunctivitis." (PMID 36763690, 2023).
colitis (6 papers, 2016 to 2022). Inflammation of the colon. "It should be noted that loss of the αv integrin as a way of blocking periostin gives play to the majority of undesirable accidents such as prenatal death, colitis, wasting, and autoimmunity." (PMID 36611844, 2022). "In summary, we were able to show that periostin is contributing to the recruitment of CCR5-positive cells to the intestine in healthy as well as murine colitis models." (PMID 36341422, 2022). "Introducing recombinant periostin elicits colitis in periostin-absence mice, and the blocking antibody specific to periostin obviously mitigates intestinal inflammatory disease." (PMID 36611844, 2022). "Our in vivo data showed that periostin exists in the normal colonic mucosa, and that its expression is significantly increased in the lamina propria of mice with colitis." (PMID 26890265, 2016). "The periostin neutralizing-antibody ameliorated the severity of colitis in DSS-treated wild-type mice." (PMID 26890265, 2016). "In conclusion, our results provide new information regarding the effects of periostin modulation in in vivo and in vitro models of colitis." (PMID 26890265, 2016). "To confirm the effects of periostin deficiency in type 1 helper T cell (Th1)-mediated murine colitis, we conducted experiments using a TNBS-induced colitis model." (PMID 26890265, 2016). "Collectively, these results suggest that blocking the activity of periostin with a nAb can attenuate intestinal inflammation in a murine model of colitis." (PMID 26890265, 2016). "Recombinant periostin induced severe colitis in Postn-/- mice, resulting in histological damage similar to that seen in the proximal and distal colon of wild-type mice." (PMID 26890265, 2016). "To confirm a role of periostin in intestinal inflammation and to address potential issues regarding Postn-/- mice, we investigated the effects of a nAb against periostin in acute murine colitis." (PMID 26890265, 2016). "To confirm a role of periostin in mediating colitis, we investigated whether external supplement of recombinant mouse periostin exacerbates the severity of colitis in Postn-/- mice." (PMID 26890265, 2016). "Administration of recombinant periostin induced colitis in Postn-/- mice." (PMID 26890265, 2016). "In addition, the administration of recombinant periostin to Postn-/- mice resulted in severe colitis, comparable with that seen in wild-type mice." (PMID 26890265, 2016). "The periostin nAb significantly attenuated the severity of colitis, as shown by the DAI." (PMID 26890265, 2016). "Although we demonstrated that Postn-/- mice exhibited clinical and histopathological improvement in a DSS-induced colitis model, it remains unclear whether periostin is an effective therapeutic target." (PMID 26890265, 2016). "To elucidate the role of periostin in IBD, we used a DSS-induced colitis model to examine intestinal inflammation in Postn-/- and wild-type mice." (PMID 26890265, 2016). "In this study, we analyzed whether there are interactions between the periostin and the CCL5:CCR5 systems in chemically induced colitis." (PMID 36341422, 2022). "The absence of periostin as well as MVC treatment helps to ameliorate the symptoms of chemically induced colitis." (PMID 36341422, 2022). "The absence of periostin as well as the treatment with MVC results in a reduced weight loss and better clinical colitis scoring, while CCL5 5p12 5m does not." (PMID 36341422, 2022). "We were able to confirm their previous finding that periostin is a driver of this disease and the absence of periostin is ameliorating the situation in chemically induced colitis in mice." (PMID 36341422, 2022). "To investigate whether periostin mediates intestinal inflammation, we conducted an in vivo study using a DSS-induced acute colitis model." (PMID 26890265, 2016).
colitis (continued). "To address this issue, we showed that recombinant periostin induced severe colitis in DSS-treated Postn-/- mice, and periostin nAb reduced colitis in DSS-treated wild-type mice, suggesting that periostin could be an effective therapeutic target for IBD." (PMID 26890265, 2016). "Both the absence of periostin and applying CCR5 antagonists were able to reduce the number of CCR5-expressing cells and ameliorated the colitis phenotype." (PMID 36341422, 2022). "Thus, our results demonstrate that reducing the signaling in both systems holds therapeutic potential and that the absence of periostin is leading to a reduction of the recruitment of CCR5-expressing cells in the murine TNBS- and DSS-induced colitis model." (PMID 36341422, 2022).
esophageal squamous cell carcinoma (6 papers, 2010 to 2024). Esophageal squamous cell carcinoma (ESCC) is a type of esophageal carcinoma (EC) that can affect any part of the esophagus, but is usually located in the upper or middle third. "The aim of the study was to explore the diagnostic values of anti-POSTN and anti-TIMP1 autoantibodies in esophageal squamous cell carcinoma (ESCC)." (PMID 35559040, 2022). "It has been demonstrated that periostin in normal esophagus is significantly lower than in esophageal squamous cell carcinoma (ESCC)." (PMID 28754000, 2017). "POSTN is mainly expressed by CAFs and its expression induces the expression of a disintegrin and metalloproteinase 17 (ADAM17) in esophageal squamous cell carcinoma cells resulting in tumor progression." (PMID 39695086, 2024).
infarction (6 papers, 2014 to 2025). A localised pathological necrosis of tissue resulting from obstruction of the blood supply usually by a thrombus, an embolus, or vascular torsion. "In this study, POSTN‐driven p16 deletion was found to enhance cardiac function and attenuate post‐infarction ventricular remodelling in MI mice, accompanied by suppressed myocardial inflammation and NLRP3 signalling activation." (PMID 40462499, 2025). "POSTN encodes periostin, a secreted ECM protein, playing a role in wound healing and post-infarction ventricular remodeling." (PMID 35845067, 2022). "Periostin is critical for stabilizing the ventricle wall after infarction, and our findings support previous work, which demonstrates that periostin expression is induced after myocardial ischemia." (PMID 24460869, 2014). "Our recent study has demonstrated that both cardiomyocytes and fibroblasts expressed periostin and ablation of periostin suppressed post-infarction myocardial regeneration by inhibiting the PI3K/GSK3β/cyclin D1 signaling pathway, suggesting a proliferating ability of periostin." (PMID 29872491, 2018).
liver disease (6 papers, 2017 to 2025). "Beyond oncology, POSTN deficiency exacerbates alcohol-associated liver disease in mice, whereas hepatic POSTN restoration is protective." (PMID 40963633, 2025). "A very high correlation of TGFBi to overall fibrotic burden was observed in the liver, indicating that loss of Stab1 or Stab2 alone does not seem to impede scavenging of POSTN or TGFBi, even in liver disease models in these mice." (PMID 37446152, 2023). "In conclusion, plasma periostin concentrations in Caucasians NAFLD patients are not influenced by the degree of liver disease, but are significantly higher in HCC." (PMID 33255560, 2020).
lung adenocarcinoma (6 papers, 2017 to 2025). A carcinoma that arises from the lung and is characterized by the presence of malignant glandular epithelial cells. "Periostin (POSTN) has been identified as a biomarker highly correlated with the risk of recurrence of lung adenocarcinoma (LUAD)." (PMID 40991535, 2025). "Our present study also corroborated these previous reports, suggesting that serum POSTN was a self-governing survival biomarker in patients with lung adenocarcinoma patients with bone metastasis." (PMID 36424413, 2022). "In lung adenocarcinoma cell lines (A549 and H1975), POSTN silencing upregulates the epithelial marker E-cadherin and downregulates the mesenchymal markers N-cadherin and Vimentin; conversely, POSTN overexpression exerts the opposite effect." (PMID 40991535, 2025).
metastatic melanoma (6 papers, 2007 to 2023). A melanoma that has spread from its primary site to another anatomic site. "The present clinical and immunohistological findings coincided well with the previous reports describing that periostin was overexpressed in the stroma in invasive and metastatic melanoma lesions in humans." (PMID 30621220, 2019). "In metastatic melanoma lesions, POSTN expression ranged from very low to very high levels compared to normal skin." (PMID 18086302, 2007).
neuroblastoma (6 papers, 2007 to 2024). Neuroblastoma (NB) is the most common solid, extracranial childhood tumor. "Thus, ALK drives neuroblastoma in part through a feedforward loop between POSTN and WNT signaling." (PMID 38451815, 2024). "Activated ALK promoted upregulation of FN1 and POSTN in our human stem cell model and in patients with amplified or mutant ALK neuroblastoma." (PMID 38451815, 2024).
ovarian tumor (6 papers, 2007 to 2023). "Elevated expression of POSTN is associated with advanced stages of ovarian tumors and poor survival of patients." (PMID 36550569, 2022). "The expression of fibronectin and periostin was also associated with the source of ovarian tumor sample: metastases showed higher expression of these proteins than primary tumor samples (χ2 test, p = 0.024 and p = 0.032)." (PMID 31936272, 2020). "The expression of fibronectin and periostin was also associated with the source of ovarian tumor sample: metastases showed higher expression of these proteins than primary tumor samples." (PMID 31936272, 2020). "Using a neutralizing antibody to periostin inhibited ovarian tumor growth and metastasis in a xenograft mouse model." (PMID 38049490, 2023). "Further, the expression of POSTN was positively correlated with that of NF-κB in ovarian tumors from patients." (PMID 36550569, 2022). "Here we show that POSTN plays an important role in ovarian tumor metastasis via cancer cells autocrine effect to enrich M2 macrophages and CAFs." (PMID 36550569, 2022). "Expression of POSTN in ovarian tumor cells was correlated significantly with advanced stage and disease recurrence." (PMID 26716408, 2016). "POSTN mRNA levels is also upregulated in ovarian tumors, and its expression in ovarian tumor cells was correlated with clinical late stage and tumor recurrence." (PMID 26716408, 2016). "In ovarian tumors, POSTN expression levels were about 15-fold higher than the average level measured in a total of seven (three separate ovaries and one pool of four) normal tissues (759 ± 708 vs 52 ± 66) (P = 0.14)." (PMID 18086302, 2007). "In ovarian tumors, tumor-derived epithelial cells and ascites, previous semi-quantitative studies reported elevated levels of periostin mRNA and protein." (PMID 18086302, 2007). "We found that the expression of POSTN was higher in the advanced stage ovarian tumors." (PMID 36550569, 2022). "We next investigated the effect of POSTN on ovarian tumor growth and metastasis." (PMID 36550569, 2022). "Our study shows that autocrine effect of cancer cells-released POSTN can trigger NF-κB and TGF-β2 pathways to enrich M2 macrophages and CAFs in ovarian tumor microenvironment." (PMID 36550569, 2022). "Furthermore, DDR2-depleted and POSTN-overexpressing CAFs co-injected with ovarian tumor cells had increased tumor burden compared to mice injected with tumor cells and DDR2 and POSTN-depleted CAFs." (PMID 35884543, 2022).
pancreatic ductal adenocarcinoma (6 papers, 2007 to 2023). An infiltrating adenocarcinoma that arises from the epithelial cells of the pancreas. "Another study has reported that calcipotriol is capable of inhibiting POSTN expression in pancreatic ductal adenocarcinoma." (PMID 30400797, 2018). "This transcriptional profile is present in mouse cells from wounds, fibrotic tissues and pancreatic ductal adenocarcinoma (PDAC) and is characterized by α-smooth muscle actin (α-SMA, Acta2) and periostin (Postn) mRNA expression." (PMID 35378690, 2022). "This study investigated the role of four previously established fibroblast markers—FAP, PDGFR, periostin, and SMA—in a large study population of 321 patients with pancreatic ductal adenocarcinoma who underwent a surgical resection with a curative intension in one of the PANCALYZE study centers." (PMID 37046710, 2023).
skin cancer (6 papers, 2018 to 2023). "Phenome-wide Mendelian randomization on 525 disease traits revealed that IRF3 and POSTN were associated with skin disorders, such as malignant neoplasm of skin and residual hemorrhoidal skin tags." (PMID 37404740, 2023). "(Section 2.1.1), POSTN was expressed in CAFs in various skin cancers (cSCC, BCC, EMPD, DFSP, Merkel cell carcinoma, and mycosis fungoides), contributing to the development of the tumor microenvironment in each cancer." (PMID 35409404, 2022). "Therefore, the association of the circulating periostin levels with advanced-stage skin lesion i.e., hyperkeratotic skin lesions observed in our study suggest the possible involvement of periostin in the pathogenesis of arsenic-induced skin cancer." (PMID 36598904, 2023). "In lesions of various skin cancers, CD163+ macrophages are a main component of TILs that can produce various chemokines by stimulating cancer-specific stromal factors such as POSTN, IL-4, and RANKL." (PMID 29643991, 2018). "POSTN could be detected in the resident area of CD163+ TAMs in MCC, which is known to be an immunoreactive malignant skin tumor." (PMID 35409404, 2022).